SPHK1 (sphingosine kinase 1)
Diseases named in the same sentence as SPHK1 in open-access papers (continued):
Sharing a sentence is not in itself a finding about the gene and the disease.
ovarian carcinoma (continued). "In conclusion, our current study provides novel evidence that ectopic expression of miR-124 significantly suppresses migration and invasion of ovarian cancer cells and down-regulates SphK1, which is a direct functional target of miR-124." (PMID 24279510, 2013). "We aimed to elucidate the involvement of miR-124 and SphK1 in migration and invasion of ovarian cancer." (PMID 24279510, 2013). "On the other hand, our data showed that overexpression of miR-124 in ovarian cancer cells suppressed cell motility via SphK1, suggesting that SphK1 was identified as a direct and functional target for miR-124 in ovarian cancer progression." (PMID 24279510, 2013). "Moreover, a SPHK1 inhibitor named SKI-II improved the effect of curcumin on the growth inhibition effect of ovarian cancer." (PMID 39875359, 2025). "Furthermore, the HA synthesis inhibitor 4‐MU reduced SPHK1 protein levels in ovarian cancer cells and HGSOC patient tissues using ex vivo tissue explant assays." (PMID 40356021, 2025). "A combination of SPHK1 inhibitors and olaparib may provide a therapeutic strategy for ovarian cancer." (PMID 39875359, 2025). "This study highlights a link between HA and SPHK1 expression in ovarian cancer." (PMID 40356021, 2025). "Considering the relationship between therapy resistance and SPHK1 in other cancers, we hypothesise that the elevated SPHK1 in relapse ovarian cancer may be contributing to therapy resistance in HGSOC." (PMID 40356021, 2025). "SPHK1 was overexpressed in tissues and cells of ovarian cancer." (PMID 39875359, 2025). "The disparate findings may be due to differences in antibody specificity, as functional ovarian cancer studies support a relationship with SPHK1 and tumour progression." (PMID 40356021, 2025). "SPHK1 has been reported to be upregulated and contributed to the survival, proliferation, migration, invasion and angiogenesis of various cancers including ovarian cancer." (PMID 39875359, 2025). "Indeed, FTY720 has been shown to inhibit the S1P-induced migration of classical Hodgkin lymphoma cells by modulating S1P1 expression and to reduce ovarian cancer cell migration by inhibiting SPHK1." (PMID 37048053, 2023). "For example, exosomal miR-124 from ovarian cancer targets sphingosine kinase 1 (SPHK1) and elevates fibroblast activating protein (FAP) and α-smooth muscle actin (α-SMA) to differentiate NFs into CAFs and controls CAF migratory and invasive capabilities, thus promoting tumor progression." (PMID 37160813, 2023). "In addition, studies have shown that Metformin can downregulate SPHK1 expression, thereby reducing S1P levels and inhibiting the development of ovarian cancer." (PMID 36823149, 2023). "While it is well known that SPHK1 phosphorylates sphingosine intracellularly to form S1P, we recently made the surprising discovery that ovarian cancer cells release extracellular vesicles (EVs) carrying SPHK1 into the TME, allowing S1P to be generated outside the cancer cell." (PMID 35289120, 2022). "SPHK1 inhibition improves the efficacy of immune checkpoint blockage therapy in ovarian cancer." (PMID 35289120, 2022). "Hence, improved immune checkpoint inhibition by targeting SPHK1/S1P signaling has potential clinical application in ovarian cancer." (PMID 36498469, 2022). "An altered SphK1/S1P/S1PR1/3 signaling axis could play a crucial role in ovarian cancer angiogenesis, although further explorations on intracellular S1P functions should be conducted, keeping in mind its biological action exerted due to S1PR binding." (PMID 36362323, 2022). "We investigated SPHK1 expression as a prognostic factor in epithelial ovarian cancer patients." (PMID 33660008, 2021). "Consistent with the role in gastric cancer, it could inhibit invasive and migratory abilities of ovarian cancer cells according to interaction with the 3′-untranslated (3′-UTR) regions of SphK1 mRNA." (PMID 34539736, 2021). "Ovarian cancer cell migration was inhibited by the SphK1-targeting miR-124." (PMID 33465049, 2021).
ovarian carcinoma (continued). "First, the authors wanted to determine whether S1P and SPHK1 promote ovarian cancer, cancer cell migration and invasion." (PMID 31534778, 2019). "Of the two, SPHK1 is better characterized and high levels of expression of this enzyme have been shown to promote oncogenic transformation, tumor growth, and drug resistance in ovarian cancer cells." (PMID 31891125, 2018). "Together, CC223 inhibits SphK1 and induces ROS production in ovarian cancer cells." (PMID 28938571, 2017). "In the current study, we provided evidence that SphK1/S1P/S1PR1/3 signaling played an important role in ovarian cancer angiogenesis and blockage of this pathway could significantly inhibit the angiogenic process of the cancer." (PMID 29088837, 2017). "The results showed a novel role of SphK1/S1P/S1PR1/3 axis within the ovarian cancer." (PMID 29088837, 2017). "SphK1 could control the release of S1P, which was able to promote the secretion of some proangiogenic cytokines in ovarian cancer cells via S1PR1 and S1PR3." (PMID 29088837, 2017). "Overall, these results indicate that the growth and seeding of ovarian cancer cells are to some extent dependent on stroma-mediated paracrine signaling, and that SPHK1 expressed in the stroma may be a major player in this process." (PMID 26716409, 2016). "miR-124 expression inversely correlated with metastasis and SphK1 in ovarian cancer, suggesting that downregulation of miR-124 may be a common mechanism to modulate S1P-induced cancer progression." (PMID 27800303, 2016). "In summary, these data indicate that SPHK1 contributes to ovarian cancer's clinical phenotype as a required mediator of CAF formation, and may serve as a viable therapeutic target." (PMID 26716409, 2016). "Loss of SPHK1 in fibroblasts abrogated the induction of myofibroblast markers αSMA and FAP, and markedly diminished the ability of fibroblasts to contract collagen gels or induce ovarian cancer cell migration and invasion." (PMID 26716409, 2016). "Evaluation of SPHK1 expression in different laser-microdissected ovarian tissue components (GSE40595) showed that CAFs expressed significantly higher levels of SPHK1 than ovarian cancer cells (p=0.0002) or normal ovarian surface epithelium (OSE, p=0.0003)." (PMID 26716409, 2016). "In the current study, we investigated whether SPHK1 mediates the differentiation of normal ovarian fibroblasts to CAFs, thereby promoting tumorigenesis in ovarian cancer." (PMID 26716409, 2016). "Additionally, the directionality of expression of miR-124 (down-regulated) and SphK1 (up-regulated) that we observed appeared to be definitive in the two high-metastasis potential ovarian cancer cell lines, SKOV3-ip and HO8910pm." (PMID 24279510, 2013). "To investigate whether MiR-124 has its inhibitory effect on migration and invasion of ovarian cancer through its target gene SphK1, we next determined to silence SphK1 and evaluated its expression by western blot in SKOV3-ip and HO8910pm cells." (PMID 24279510, 2013). "Also, clinical ovarian cancer samples were used to confirm the relationship between the endogenous expression levels of SphK1 and miR-124." (PMID 24279510, 2013). "Besides, we also found that the ovarian cancer samples and metastatic ovarian cancer tissues showed a high level expression of SphK1." (PMID 24279510, 2013). "Also, our results provided another mechanism for modulating the protein expression of SphK1 in ovarian cancer cells." (PMID 24279510, 2013). "However, the effect and mechanism of SPHK1 on olaparib sensitivity in ovarian cancer were obscure." (PMID 39875359, 2025). "Thus, SPHK1 inhibits ferroptosis in ovarian cancer cells through P65 regulated NRF2." (PMID 39875359, 2025). "Our previous work demonstrated that mislocalised SPHK1, caused by loss of a negative regulator protein, calcium and integrin binding protein 2 (CIB2), promoted tumour growth, metastasis and chemotherapeutic resistance in ovarian cancer cell lines and a xenograft mouse model." (PMID 40356021, 2025).
ovarian carcinoma (continued). "Among the upregulated DEGs in the niraparib-treated group, SPHK1 was the most significantly changed gene, but the difference in expression between the tumor and the corresponding normal tissue was inconspicuous in breast and ovarian cancers according to the TCGA and GTEx databases." (PMID 36793373, 2023). "Moreover, we used siRNA to knockdown SphK1 in ovarian cancer cells." (PMID 33931106, 2021). "Furthermore, these changes of phenotypes induced by SphK1 blockage could be reversed by exogenous S1P addition, which suggested that SphK1 blockage attenuated the angiogenic potential of ovarian cancer cells partly through inhibition of S1P." (PMID 29088837, 2017). "Therefore, we hypothesized that expression of SPHK1, the enzyme that produces S1P, would also be altered in ovarian cancer." (PMID 26716409, 2016). "Then, high-throughput sequencing was performed on the parental SKOV3 and SK/OLA cell lines, the results showed that sphingosine kinase 1 (SPHK1) was one of the upregulated genes and was related to the PFS and OS in ovarian cancer patients." (PMID 39875359, 2025). "We analysed SPHK1 gene expression in OSE, FT, different ovarian cancer types and metastatic ovarian cancer tissues in the GENT2 database." (PMID 40356021, 2025). "We conclude that SPHK1 inhibition triggers ferroptosis by restricting NF-κB-activated NRF2 transcription, thereby enhancing olaparib sensitivity in ovarian cancer." (PMID 39875359, 2025). "We observed positive correlations between SPHK1 expression and CD44 in ovarian cancer patient tissues." (PMID 40356021, 2025). "SPHK1 inhibition triggers ferroptosis by restricting NF-κB-activated NRF2 transcription, thereby enhancing olaparib sensitivity in ovarian cancer." (PMID 39875359, 2025). "Sphingosine kinase 1 (SPHK1) drives NRF2 transcription and suppresses ferroptosis via NF-κB p65 activation, thereby conferring resistance to olaparib in ovarian cancer cells." (PMID 40342999, 2025). "In a complementary approach, we used siRNAs specific to SPHK1, S1PR1, and S1PR2 to knock down those proteins’ expression in ovarian cancer cells." (PMID 35289120, 2022). "FSH induces the phosphorylation of both SPHK1 and SPHK2 enzymes to regulate the survival and growth of ovarian cancer cells via the ERK1/2 pathway." (PMID 35565311, 2022). "Both SPHK1 and SPHK2 have been shown to be equally responsible for follicle-stimulating hormone (FSH)-induced cell proliferation of epithelial ovarian cancer." (PMID 35565311, 2022). "Immunoblotting of whole cell lysates (WCLs) and EVs isolated from four ovarian cancer cell lines (HeyA8, OVCAR5, NIH‐OVCAR3, and OVCAR4) demonstrated that SPHK1 isoform 2 was highly expressed in the secreted EVs compared to the WCLs of all four cell lines." (PMID 35289120, 2022). "Furthermore, combining anti‐PD‐1 antibody with PF543 increased mouse survival and decreased tumor burden, suggesting that a combination of an S1P/SPHK1 blocker with anti‐PD‐1 therapy may improve the efficacy of immune checkpoint blockers in human ovarian cancer." (PMID 35289120, 2022). "Notably, SphK1 was found upregulated in many different cancers, such as kidney cancer, prostate cancer, liver cancer, colorectal cancer, gastric cancer, uterine cancer, ovarian cancer, lung cancer, breast cancer, lymphoma, glioblastoma, small bowel cancer, and myeloid leukemia." (PMID 34069611, 2021). "Further the expression of SPHK1 and S1PR1/3 was correlated with microvascular density of ovarian cancer tissue, and inhibition of SPHK1 or S1PR1/3 attenuated angiogenic potential and angiogenic factor secretion of ovarian cancer cells in vitro and in vivo." (PMID 31891125, 2018). "In ovarian cancer cell lines, FTY720 inhibited SPHK1 activity, angiogenesis, invasion, and proliferation." (PMID 31891125, 2018). "Collectively, the current study showed a novel role of SphK1/S1P/S1PR1/3 axis within the ovarian cancer, suggesting a new target to block ovarian cancer angiogenesis." (PMID 29088837, 2017).
ovarian carcinoma (continued). "We investigated the SphK1, SphK2, MVDCD34 and MVDCD105 expression in samples from ovarian cancer patients." (PMID 29088837, 2017). "Knockout of SPHK1 also altered the ability of TRS3 cells to promote the migration and invasion of ovarian cancer cells in vitro." (PMID 26716409, 2016). "Knockout or pharmacological inhibition of SPHK1 in ovarian fibroblasts attenuated TGF-β-induced expression of CAF markers, and reduced their ability to promote ovarian cancer cell migration and invasion in a coculture system." (PMID 26716409, 2016). "However, it is unclear whether SphK1 is responsible for malignant transformation of ovarian cancer." (PMID 24279510, 2013). "Interestingly, neutralizing S1P, the product of SPHK1 enzymatic activity, with a specific monoclonal antibody was remarkably effective in slowing progression of cancers, such as lung, colon, breast, melanoma and ovarian cancers in murine xenograft and allograft models." (PMID 21936950, 2011). "SPHK1 was upregulated in SK/Ola cells and was related to the PFS and OS in ovarian cancer patients." (PMID 39875359, 2025). "Survival analysis showed that SPHK1 was related to the PFS and OS of ovarian cancer patients." (PMID 39875359, 2025). "Given the effect of SPHK1 inhibitor on tumor cells and T cells, we hypothesized that administering PF543 along with anti‐PD‐1 antibody should improve anti‐PD‐1 therapy for ovarian cancer by increasing the antitumor responses of T cells." (PMID 35289120, 2022). "Notably, by stimulating phosphorylation of sphingosine kinase 1 (SphK 1) and 2 (SphK 2), FSH induces proliferation of ovarian cancer cells in epithelial ovarian cancer." (PMID 35002517, 2022). "Additionally, the expression levels of both phospho-SphK1 and phospho-SphK2 were closely correlated with the expression level of follicle-stimulating hormone receptor (FSHR) in ovarian cancer tissues." (PMID 32796926, 2020). "Moreover, sphingosine kinase 1 (SPHK1), a key enzyme for the conversion of sphingosine to S1P, is overexpressed in ovarian cancer tissues and cultured ovarian cancer lines." (PMID 28460443, 2017). "We found that knockdown of SphK1, but not SphK2, by siRNA inhibited S1P secretion in ovarian cancer cells." (PMID 29088837, 2017). "To determine whether induction of SPHK1 expression was mediated by TGF-β produced by ovarian cancer cells, we stimulated TRS3 cells with ovarian cancer cell conditioned medium treated with an anti-TGF-β antibody or an IgG control." (PMID 26716409, 2016). "Importantly, in ovarian cancer, the mTORC1/2 inhibitor WYE-132 reduced SphK1 activity, which induced cytotoxicity and diminished in vivo cell growth." (PMID 27800303, 2016). "Additionally, SPHK1 expression was increased in ovarian cancer patients (serous, grade III) who did not respond to combination platinum and taxane chemotherapy treatment." (PMID 40356021, 2025). "Inhibition of SphK1, by pharmacological tools as SKI-II (2-(p-Hydroxyanilino)-4-(p-chlorophenyl)thiazole) or by RNA interference, dramatically enhanced curcumin-induced apoptosis and growth inhibition in ovarian cancer cells via Cer production and p38 activation and Akt inhibition." (PMID 30037082, 2018). "Moreover, SphK1, but not SphK2, siRNA transfection significantly attenuated the angiogenic potential and angiogenic factor secretion of ovarian cancer cells, which suggested that SphK1, but not SphK2, was involved in ovarian cancer angiogenesis." (PMID 29088837, 2017). "Moreover, SphK1, but not SphK2 knockdown, resulted in the suppression of the angiogenic potential and the angiogenic factor secretion of ovarian cancer cells, indicating that SphK1, but not SphK2, was responsible for ovarian cancer angiogenesis." (PMID 29088837, 2017). "SphK1, but not SphK2, blockage significantly decreased S1P release from ovarian cancer cells." (PMID 29088837, 2017).
ovarian carcinoma (continued). "In vitro, the angiogenic potential and angiogenic factor secretion of ovarian cancer cells could be attenuated by SphK1, but not SphK2, blockage and were restored by the addition of S1P." (PMID 29088837, 2017). "Thus, inhibition of SphK1 activity with corresponding decrease of S1P levels induced apoptosis in acute myeloid leukemia (AML) cells, and diminished in vivo cell growth of ovarian cancer." (PMID 27800303, 2016). "To investigate if SPHK1 expression in ovarian fibroblasts is induced by epithelial-stromal interaction, we cocultured immortalized human normal ovarian fibroblast cell lines (TRS3 and INOF) with fluorescently labeled ovarian cancer cells for 48 hours, and then separated by FACS." (PMID 26716409, 2016). "The expression level of SphK1, but not SphK2, was closely correlated with the microvascular density (MVD) of ovarian cancer tissue." (PMID 29088837, 2017).